CLDN4 (claudin 4)
Diseases named in the same sentence as CLDN4 in open-access papers (continued):
Sharing a sentence is not in itself a finding about the gene and the disease.
tumor (163 papers, 2005 to 2026). "Claudin-4, a tight junction protein frequently overexpressed in epithelial tumors, has been associated with tumor progression and resistance to chemotherapy." (PMID 41464164, 2025). "In PDAC, the overexpression of claudins, particularly claudin-4, has been associated with tumor invasion and metastasis." (PMID 39869563, 2025). "Increased claudin-4 expression has been associated with higher tumor grade and with basal like phenotype." (PMID 39687048, 2024). "EXs from EOC patients also have higher concentrations of Claudin 4 associated with tumor stage and CA125 levels." (PMID 39125689, 2024). "A meta-analysis demonstrated that CLDN4 expression was associated with an increased pathological tumor (pT) classification, tumor size, and lymph node metastasis." (PMID 37109309, 2023). "The loss of claudin-4 expression significantly increased caspase-3 activation and reduced tumor cell migration." (PMID 36675266, 2023). "In solid organoids, there was also a significant reduction in the expression of Cldn7 and Cldn4, which belong to the tight junction protein family previously associated with tumor differentiation, liver metastasis, and decreased survival in patients with PDAC." (PMID 36828915, 2023). "Only one epithelial-associated gene (CLDN4) was more highly expressed in CTCs compared to tumours, and one epithelial-associated gene (KLK3) was expressed at lower levels." (PMID 34206049, 2021). "Loss of claudin-4 expression was correlated with poor tumor differentiation and significantly increased the likelihood of poor cancer-related survival." (PMID 34638619, 2021). "Increased claudin 4 expression is associated with poor prognosis, high tumour grade and lymph node and distal metastasis." (PMID 31044387, 2020). "Given that CLDN4 expression varied with tumor histological grading, its association with other clinicopatholgical parameters was assessed by classifying the analyzed cases as either ‘differentiated’ or ‘undifferentiated’." (PMID 31040910, 2019). "The average number of metastatic nodules was 4.11 ± 1.64 in the miR-596+CLDN4 group and 4.57 ± 1.38 in the miR-3620-3p+CLDN4 group, showing a rescue of the tumor-promoting effects caused by CLDN4 overexpression." (PMID 28819095, 2017). "Using meta-analysis, we have also found that CLDN4 expression is associated with increasing pT category, tumor size, and lymph node metastasis in patients with GC36." (PMID 28819095, 2017). "It controls the expression of the adherents junction gene E-cadherin and the tight junction gene claudin 4 (Cldn4) and has been linked to both pro and anti-tumour activity." (PMID 27124473, 2016). "Significant associations between high claudin-4 expression and more aggressive tumor cell behavior have been reported by several laboratories." (PMID 27724921, 2016). "Exposure to ionizing radiation in the past was associated with abnormalities in claudin expression in PTC patients and the gain of chromosome band 7q11 encoding both claudin-3 and claudin-4, which may promote tumor invasiveness and metastasis." (PMID 39458944, 2024). "On the contrary, levels of Cldn1,Cldn4,Cldn6,Cldn9,Cgn,F11r, and Cdh1, associated with exacerbated inflammation, perturbation of the TJ assembly, and even with mesenchymal transformation or tumour progression, were overexpressed." (PMID 37794493, 2023). "It is thought that overexpression of CLDN4 caused by H. pylori might result in the formation of tight junctions, which might provide an isolated tumor microenvironment mediated through the barrier function of the tight junction." (PMID 31040910, 2019). "Both the disruption of claudin-4 activity and the loss of claudin-4 expression significantly increased tumor cell caspase-3 activation (4 to 10-fold, respectively) in response to the apoptotic inducer staurosporine and reduced tumor cell migration by 50 %." (PMID 27724921, 2016).
tumor (continued). "As these events are also related to tumor size, this might explain the finding of the significant association of Claudin-4 and larger tumor size." (PMID 25417118, 2014). "The important issue is whether loss of CLDN1 and CLDN4 plays a significant role in cell–cell adhesion and tumour differentiation." (PMID 15743508, 2005). "We found that tumor lumps in the CLDN4 group were significantly larger than in the pEX2-NC group, and that miR-596 and miR-3620-3p could partially reduce the growth trend caused by CLDN4." (PMID 28819095, 2017). "In addition, positive CLDN4 expression was associated with higher tumor grade (P = 0.003)." (PMID 25393310, 2014). "We prioritized FKBP5 (HP pharmacodynamics) and CLDN4 (tumor baseline) as the main candidates; TSPO and SGK1 are reported as exploratory." (PMID 41614938, 2026). "Primary markers—FKBP5 and CLDN4 carry the headline: FKBP5 reports on the HP-engaged steroid/PPAR axis in adjacent tissue, while CLDN4 reports on tumor epithelial remodeling that underlies invasion." (PMID 41614938, 2026). "In comparison, CLDN4 represents a primary tumor pathway of epithelial junction remodeling and ECM interaction." (PMID 41614938, 2026). "Monoclonal antibody (e.g. KM3900) targeting CLDN4 induces cytotoxicity and disrupts tumor tight junctions, enhancing therapy efficacy." (PMID 41399659, 2026). "Patient files were accessed to obtain information on age, tumor size and grading, lymph node involvement, metastasis, Ki67, and CLDN4 expression." (PMID 40487255, 2025). "In the tumor region, DEGs included ECM-related genes such as MMP7, LCN2, chemokine CXCL5, and tumor markers CLDN4 and MUC4." (PMID 40303346, 2025). "Analysis of the positive pixel was carried out to quantify the signals associated with CLDN4 and CEACAM5, revealing that CLDN4 expression was significantly higher in tumor samples compared to surrounding healthy tissues from the same patients (p < 0.5)." (PMID 40868067, 2025). "In prostatic adenocarcinoma elevated expression of CLDN4 is correlated with high tumor grade, lymph vascular invasion, and positive lymph node metastasis." (PMID 40687428, 2025). "Only rare PEMs show claudin-4 expression but with a characteristic staining pattern, represented by a focal (<10% of tumor cells) and granular/dot-like cytoplasmic stain." (PMID 39941848, 2025). "Beyond its structural function, Claudin-4 contributes to tumor invasion, motility, angiogenesis, and resistance to apoptosis." (PMID 41464164, 2025). "Our data indicate that claudin-4 protects tumor genome integrity by modulating the crosstalk between the nucleus and the cell cycle, leading to resistance to genomic instability formation and the effects of genomic instability–inducing agents." (PMID 39625235, 2025). "Knockdown of CLDN3 or CLDN4 in tumor cell lines results in reduced tight junction formation and increased invasiveness." (PMID 38326579, 2024). "We found that claudin-4 promotes a tolerance mechanism for genomic instability through micronuclei generation in tumor cells." (PMID 38867360, 2024). "High-resolution, multiplex imaging analysis of KRT8, CLDN4 and pan-cytokeratin (PanCK) showed that KACs were enriched in tumour-adjacent normal regions (TANs) and were found immediately next to malignant cells showing high expression of KRT8 and CLDN4." (PMID 38418883, 2024). "TACSTD2 and EpCAM were previously reported to be associated with cell adhesion and metastasis of tumor, implying the effect on recurrent MPE accompanied with CLDN4." (PMID 38629624, 2024). "Four weeks after inoculation in SCID (severe combined immunodeficiency) mice, the tumor growth of T47D:CLDN4–/– and MDA-MB-231:CLDN4 xenografts was decreased and increased compared with that of their parental cell xenografts, respectively." (PMID 37059993, 2023). "Of note, invasion around the tumor, namely the budding of cancer cells, was significantly hampered in T47D:CLDN4–/– xenografts compared with T47D xenografts." (PMID 37059993, 2023).
tumor (continued). "CLDN4 knockout mice exhibit a hyperproliferation of the urothelium, while activation of the tumor suppressor gene cancer-related regulator of actin dynamics (CRAD) is associated with CLDN4 upregulation." (PMID 36982569, 2023). "CLDN4 helps to maintain the tumor microenvironment by forming TJs and acts as a barrier to the entry of anticancer drugs into tumors." (PMID 36982569, 2023). "VEGF and IL-8, cancer cell-derived angiogenic factors, are upregulated by CLDN4 and their accumulation in tumors promotes tumor angiogenesis." (PMID 36982569, 2023). "To examine the tumor-targeting ability of C-LPs in vivo, we intravenously injected Cy5.5-labeled D@LPs or D@C-LPs into athymic nude mice bearing CLDN4-positive KPC960 tumors and monitored the in vivo biodistribution of liposomes over time." (PMID 37237291, 2023). "Claudin-4 (CLDN4) is an integral membrane protein, the expression of which is frequently altered in various tumour tissues, including GC." (PMID 38201579, 2023). "Based on this study, we can explore the prognosis of patients by assessing the expression of Claudin-4 and circulating tumor cells in peripheral blood." (PMID 37465316, 2023). "Even with these considerations, it is emphasized that targeting CLDN4 is an attractive therapeutic approach that offers pleiotropic benefits, including cancer cytotoxicity, reprogramming tumor microenvironments, and improvement of drug delivery." (PMID 36982569, 2023). "Most patients with high Claudin-4 expression had a tumor >5 cm (51.9% vs. 7.9%, p < 0.001 vs. low Claudin-4 expression)." (PMID 37465316, 2023). "The barrier function of CLDN4 leads to the accumulation of lactate within the tumor microenvironment and maintains an acidic environment around the cancer cells." (PMID 36982569, 2023). "The changes in the expression of Claudin-4 can modify the structure of the tight junctions and adhesion between cells, leading to tumor metastasis and spread." (PMID 37465316, 2023). "In recent years, claudin has been increasingly studied, and many claudin proteins, such as claudin-18.2, claudin-4, and claudin-7 have been demonstrated to be ideal targets for tumor therapy." (PMID 36959784, 2023). "The overexpression of CLDN4 is correlated with the presence of liver metastases from PC as well as with the histological grade of the tumour." (PMID 38201579, 2023). "Claudin proteins are extensively studied, and various claudin proteins, including claudin-1, claudin-4, and claudin-18.2 have high specificity and sensitivity in tumor diagnosis." (PMID 36959784, 2023). "In particular, Claudin-4 can directly or indirectly promote tumor metastasis through the second extracellular loop structure." (PMID 37465316, 2023). "CPE peptide, CPE17, can bind to exposed CLDN4 on tumor cells while it is difficult to bind hidden CLDN4 on normal cells." (PMID 37237291, 2023). "In a subcutaneous mouse tumor model, CDDP suppressed tumor growth after CLDN4 knockdown, whereas increasing CLDN4 expression by AZA treatment enhanced tumor growth." (PMID 35742959, 2022). "CPE gene transfer in vitro and in vivo, using the bacterial wild-type CPE cDNA (wtCPE) or optCPE cDNA, selectively killed tumor cells overexpressing Claudin-4." (PMID 36077843, 2022). "Up to 100% cytotoxicity in tumor lines expressing Claudin-4 specifically was reported 72 h following the transfer of CPE genes." (PMID 36077843, 2022). "Since many tumor cells show elevated levels of Claudin-4 and Claudin-4 has a significant binding efficiency to CPE, CPE is applicable for drug delivery." (PMID 36077843, 2022). "It would therefore be advisable to re-evaluate the patients with an increased expression of claudin-2 and a reduced expression of claudin-4 at shorter intervals in the follow-up assessment of the tumor." (PMID 36232536, 2022). "Relative to paracancerous tissues, clinical CRC tumor tissue samples exhibited CLDN4 and CLDN11 upregulation and downregulation, respectively." (PMID 35281827, 2022).
tumor (continued). "c-CPE conjugated to nanoparticles and delivered intraperitoneally is by far the most successful method shown to localize c-CPE to tumor cells highly expressing Claudin-4 and to further reduce cytotoxicity." (PMID 36077843, 2022). "Patients with CLDN4 overexpression develop various clinicopathological characteristics including high tumor grade, poor prognosis and shorter disease-free survival." (PMID 33801373, 2021). "Chronic administration of DMH revealed an increase in the expression of tightening claudin-3 (273 ± 65% vs. control, n = 4) and claudin-4 (222 ± 31% vs. control, n = 5) in tumor tissue." (PMID 34638619, 2021). "Nonetheless, a number of monoclonal antibodies against human claudin 4 have been developed that show both anti-tumor effects and induction of chemosensitivity in vivo." (PMID 34522225, 2021). "CTTN overexpression (βadj. = 0.253, P < 0.05), CLDN-1 (βadj. = 0.345, P < 0.01), and CLDN-4 (βadj. = 0.338, P < 0.01) were significantly correlated to the larger tumor dimension in the models adjusted for potential covariates." (PMID 33407452, 2021). "The overexpression of CTTN, CLDN-1, and CLDN-4 genes was correlated positively with the extent of tumor size." (PMID 33407452, 2021). "The increased activity seen for co-administered agents has suggested the induction of chemosensitivity by anti-claudin 4 agents in addition to its anti-tumor effects." (PMID 34522225, 2021). "Sasaki and co-workers investigated the effects of anti-claudin 4 antibody 4D3 in combination with FOLFIRINOX in a PDAC subcutaneous murine tumor model." (PMID 34522225, 2021). "We have also reported that impairment of the barrier function of tight junctions by an anti-CLDN4 antibody raises the pH of the tumor microenvironment and reduces the stemness of cancer cells." (PMID 32998265, 2020). "The range of CD44 expression in primary SCCOHT tumors was more dynamic than with Claudin-4, shown by select tumor cores that moderately expressed CD44 (range of CD44/DAPI in SCCOHT = 0.22–31.9%)." (PMID 33355532, 2020). "In particular, claudin-4 and claudin-7 transcript levels were increased by over 2-fold in normal fallopian tubes compared to tumor samples (both p < 0.001), whereas claudin-3 showed a 1.18-fold increase in fallopian tubes compared to HGSOCs (p = 0.305)." (PMID 32850397, 2020). "We observed that the progression, including tumor invasion and nodal metastasis, was more pronounced in nuclear CLDN4-positive cases than in cases where CLDN4 were observed in the cell membranes." (PMID 32064037, 2020). "Since Clostridium perfringens enterotoxin (CPE) is a well-known factor that impairs CLDN4, bacterial genome-specific sequences were amplified by PCR and examined for the presence of anaerobic bacteria in tumor tissues." (PMID 32064037, 2020). "SPECT/CT imaging of BALB/c nude mice bearing PSN-1 or HT1080 tumor xenografts was performed to determine the claudin-4–targeting ability of these peptides in vivo." (PMID 32414951, 2020). "In the case of PyMT tumor cells, higher levels of Ltf, Spp1, Anxa1 and Cldn4 distinguish them from Neu and BRCA1-null tumor cells, and some of these genes have been associated with luminal progenitors." (PMID 32840210, 2020). "We first examined 91 cases of human PDC by immunohistochemistry and found that CLDN4 expression was correlated with tumor invasion, nodal metastasis, and distant metastasis." (PMID 31498559, 2019). "Autoradiography of frozen xenograft sections revealed higher accumulation of [111In]anti-claudin-4 within Panc-1 tumours compared with [111In]mIgG." (PMID 28842811, 2018). "Immunofluorescence microscopy experiments on tissue sections obtained from Panc-1 or HT1080 xenograft tumours showed the differential claudin-4 status in these two cell lines that was maintained when transferred to an in vivo setting." (PMID 28842811, 2018).
tumor (continued). "Taken together, these measurements strongly indicate that uptake of [111In]anti-claudin-4 in Panc-1 tumour xenografts was primarily mediated by claudin-4 expression." (PMID 28842811, 2018). "Total uptake of [111In]anti-claudin-4 mAb in Panc-1 tumours at 72 h p.i. was approximately 3-fold higher compared with experimental controls." (PMID 28842811, 2018). "Tumour uptake of [111In]anti-claudin-4 in Panc-1 xenografts was significantly higher compared to that obtained with [111In]mIgG at all time points (P < 0.01) and with [111In]anti-claudin-4 in HT1080 tumours (P < 0.01)." (PMID 28842811, 2018). "The ability of [111In]anti-claudin-4 mAb to selectively target claudin-4 was assessed using two human xenograft tumour models with differential claudin-4 status in mice." (PMID 28842811, 2018). "Despite exhibiting a low binding affinity (1.93 ± 0.59 μM), this radiotracer revealed claudin-4-mediated tumour uptake in a variety of human cancer xenograft and genetically engineered models which were all found to have upregulated claudin-4 expression." (PMID 28842811, 2018). "Our previous study showed that CLDN4 regulates the permeability of tumor cells both in vitro and in vivo." (PMID 30647838, 2018). "Claudin-4 (CLDN4) is a major epithelial tight junction protein overexpressed in many cancers to maintain the tumor environment." (PMID 30647838, 2018). "Claudin 4 has a correlation with tumour angiogenesis, and can be used as a treatment target protein, which was consistent with our research results." (PMID 28376864, 2017). "Further more, the WB results proved that the Claudin 1, Claudin 4, and Claudin 7 proteins were closely related to the mechanism of tumour growth and metastasis." (PMID 28376864, 2017). "Lastly, WB showed that Claudin 1, Claudin 4, and Claudin 7 were closely related to tumour growth and metastasis." (PMID 28376864, 2017). "Claudin 1, Claudin 4, and Claudin 7 were the main proteins contributing to the oridonin anti-tumour effect based on the inhibition of angiogenesis." (PMID 28376864, 2017). "Research suggested that Claudin 4 plays an important role in tumour growth and malignancy via the control of cell proliferation, migration, apoptosis, and metastasis." (PMID 28376864, 2017). "The mean tumor volumes in the miR-596+CLDN4 and miR-3620-3p+CLDN4 groups were both smaller (0.87 ± 0.31 cm3 and 0.75 ± 0.38 cm3, respectively) than in the CLDN4 overexpressing group." (PMID 28819095, 2017). "For SGC-7901 cells, the mean tumor volume at the time of death in mice injected with CLDN4 overexpressing cells was 1.34 ± 0.39 (mean value ± s.d)." (PMID 28819095, 2017). "Does claudin-4 increase the motility and survivability of ovarian and perhaps other types of tumor cells?" (PMID 27724921, 2016). "When either population was injected into the peritoneal cavity of mice, only the CD44+ (high claudin-4 expressing tumor cells) exhibited a strong migratory potential." (PMID 27724921, 2016). "The expression of claudin-4 mRNA in this stem-like population of tumor cells is significantly higher than the CA125-positive tumor cell population that is sensitive to platinum treatment." (PMID 27724921, 2016). "We have shown that overexpression of claudin-4 reduces tumor cell sensitivity to apoptosis and enhances tumor cell migration." (PMID 27724921, 2016). "Disruption of extracellular loop activity of claudin-4 in the presence of DFYNP enhanced tumor cell sensitivity to apoptosis, inhibited tumor cell motility, and ultimately led to reduced tumor burden in vivo." (PMID 27724921, 2016). "In fact, claudin-4 is expressed at higher levels in most tumor cells compared to the normal epithelium of origin." (PMID 27724921, 2016). "Although CPE is predicted to act through a different mechanism than DFYNP, effects of both strategies demonstrate the utility of targeting claudin-4 to reduce tumor cell survival." (PMID 27724921, 2016).